SIRT3 (sirtuin 3)
Diseases named in the same sentence as SIRT3 in open-access papers (continued):
Sharing a sentence is not in itself a finding about the gene and the disease.
tumor (continued). "SIRT3 acts as a tumor suppressor by destabilizing HIF-1α, thereby inhibiting these oncogenic processes." (PMID 39682281, 2024). "The depletion of SIRT3 facilitates a metabolic shift towards increased glycolysis, elevated mitochondrial ROS production and diminished autophagy, all of which favor tumor progression." (PMID 39682281, 2024). "SIRT3 is highly expressed in CRC cells leading to tumor resistance and poor overall survival, with the reduction of protein expression resulting in cytotoxicity, cell death and impaired metabolic state and aggressiveness." (PMID 38811901, 2024). "In human cancers, SIRT3 has been found to function as a tumor suppressor by preventing metabolic shifts that promote tumor growth." (PMID 39501597, 2024). "In some types of cancer, SIRT3 functions as an oncogene, whereas in other types, it acts as a tumor suppressor, inducing cancer cell death under stress conditions." (PMID 36594098, 2023). "SIRT3 was found to regulate AMPK expression in tumour cells and also AMPK was found to have a direct stimulatory effect on SIRT3 expression." (PMID 37996927, 2023). "In this study, SIRT3 overexpression inhibited the proliferation, invasion, and migration of tumor cells under a hypoxic environment." (PMID 37747648, 2023). "There is evidence to suggest that SIRT3 expression reduces miR-31-dependent tumour invasion and migration." (PMID 36815979, 2023). "Immunohistochemistry and enzyme-linked immunosorbent assay were performed to detect SIRT3 expression and the expression levels of IL-1β, TNF-α, and IL-6, respectively, in tumor tissues." (PMID 37747648, 2023). "We found that intestinal epithelial cell-specific ablation of Sirt3 promotes primary tumor growth via stabilizing mitochondrial LONP1." (PMID 36739437, 2023). "In some types of cancer SIRT3 functions as a tumor promoter by lowering ROS levels to maintain cell proliferation, other studies describe SIRT3 as a tumor suppressor, as it can promote apoptosis in cancer cells under stress conditions." (PMID 37608150, 2023). "The expressions of SIRT3 in tumor tissues were considerably lower in the Hypoxia group than in the Control group and significantly higher in the SIRT3 mimics group than in the Vector group." (PMID 37747648, 2023). "This study found that the overexpression of SIRT3 in a hypoxic environment, both in vivo and in vitro, inhibited tumor cell proliferation, invasion, migration, ROS, and inflammation levels." (PMID 37747648, 2023). "We revealed that SIRT3 increases ALDH1L2 activity, thus enhances CRC proliferation, which is consistent with previous reports on the tumor-promoting role of SIRT3 in CRC." (PMID 37507016, 2023). "Sirtuin-3 is a tumor-suppressing gene and L. reuteri can inhibit the downregulation of Sirt3 expression during colorectal tumorigenesis." (PMID 37662007, 2023). "In this study, the overexpression of SIRT3 significantly decreased the expression of FPR1 in tumor cells under a hypoxic environment." (PMID 37747648, 2023). "SIRT3 promotes tumour cell survival via the activation of the telomerase enzyme which allows unlimited tumour cell replication with further tumour growth." (PMID 37996927, 2023). "SIRT3 acts as a tumor suppressor by suppressing ROS through the activation of antioxidant defense by the manganese superoxide dismutase (MnSOD), an essential mitochondrial antioxidant enzyme, and regulating HIF-1." (PMID 36769283, 2023). "The PD-L1-integrin axis also increases the glucose metabolism and tumor cell proliferation through SNAI1-mediated downregulation of SIRT3 in CC, suggesting that the reprograming of Warburg effect is essential for the tumor cell dissemination." (PMID 36905477, 2023). "As a tumor suppressor, SIRT3 can participate in various metabolic processes by deacetylating downstream protein substrates." (PMID 37747648, 2023). "Our results also showed that the expression of Sirt3 in several tumor samples from CRC patients was lower than the corresponding adjacent tissues." (PMID 36739437, 2023).
tumor (continued). "High expression of SIRT3 in DLBCL tumor cells can replenish the TCA cycle and generate ATP to create biomass, which supports tumor growth." (PMID 37367892, 2023). "SIRT3 acted as a tumor suppressor gene and its downregulation promoted tumor cell migration and metastasis." (PMID 37407961, 2023). "Our results sustain the notion that Sirt3 is a tumor-suppressor to maintain the appropriate ubiquitination and degradation of oncogene LONP1." (PMID 36739437, 2023). "SIRT3 maintains mitochondrial stability and promotes an optimal level of reactive oxygen species (ROS) essential for the survival of tumour cells which is achieved via the regulation of metabolism and cellular glycolysis." (PMID 37996927, 2023). "SIRT3 appears to play a dual role in cancer cells, acting as both a tumor suppressor and a promoter." (PMID 37646973, 2023). "SIRT3 functions as a tumor-suppressor in characteristic aerobic glycolysis-dependent tumors by maintaining flux through aerobic respiration, a known characteristic of non-proliferating cells; however, SIRT3 is also overexpressed in certain tumors." (PMID 37238738, 2023). "In the 217 human CRC tumor samples, SIRT3 immunostaining was high in 51.6% (n = 112) and low in 48.4% (n = 105)." (PMID 36594098, 2023). "Sirt3 has been generally recognized as a tumor suppressor which represses oxidative stress and destabilizes HIF-α." (PMID 36739437, 2023). "Compared with the Vector group, the mRNA and protein expression levels of SIRT3 were significantly up-regulated in tumor tissues of the SIRT3 mimics group." (PMID 37747648, 2023). "Together, these results show a correlation of Sirt3, MnSOD acetylation status, and ROS detoxification activity, as well as mitochondrial metabolic stress with carcinogenesis, implicating Sirt3 as a tumor suppressor." (PMID 35453320, 2022). "In different types of cancers, SIRT3 has dichotomous role in cancer process as a tumor promoter or suppressor." (PMID 35433629, 2022). "Currently, owing to its dual role in cancer, SIRT3 has attracted lots of attention from researchers, particularly in the terms of regulating the metabolism reprogramming of tumor cells, involving cancer metastasis, drug resistance, and other aspects." (PMID 35832551, 2022). "Pathologic SIRT3 expression involves complex molecular signaling pathways and affects tumor metabolism, metastasis, and prognosis." (PMID 35832551, 2022). "Another study showed that, among clinical characteristics, SIRT3 expression was correlated with lymph node metastasis, grade, and tumor size." (PMID 35571098, 2022). "When SIRT3 is highly expressed, tumor cells can balance ROS production, and become more resistant to chemotherapy drugs." (PMID 35832551, 2022). "SIRT3 controlling mitophagy represents an important mechanism to prevent mitochondrial dysfunction and apoptosis in tumor cells under hypoxia." (PMID 35387119, 2022). "This review is focused on the role of sirtuin 3 as a target for tumor cell elimination and how mitochondria and reactive oxygen species (ROS) are implicated in this process." (PMID 35938164, 2022). "On the one hand, SIRT3 inhibits the Warburg effect, tumor cell proliferation and metastasis to serve as a tumor suppressor." (PMID 35571098, 2022). "The expression of SIRT3 is negatively related to clinicopathological variables, including tumor invasion, differentiation, and stage." (PMID 35571098, 2022). "Sirt3 suppression in primary mouse embryo fibroblasts (MEFs) or tumor cell lines stimulates cell proliferation and augments HIF1α protein stabilization and its transcriptional activity under hypoxic conditions." (PMID 35938164, 2022). "The mechanism of action of SIRT-3 as a tumor suppressor seems to be different depending on the tumor type." (PMID 36080416, 2022). "Acting as a modulator of cell metabolism, SIRT3 displays tumor-suppressing and tumor-promoting features in cancer by regulating the acetylation level of multiple mitochondrial proteins." (PMID 35832551, 2022).
tumor (continued). "Another study showed that SIRT3 represses tumor growth by downregulating HIF-1α and reducing ROS accumulation." (PMID 36211825, 2022). "While Sirt3 and Sirt4 have been identified as tumor suppressors, Sirt5 has been reported to be a tumor promoter in various types of cancer." (PMID 35963851, 2022). "SIRT3 has also been suggested as a mitochondrial tumor suppressor, but overall, the main role of SIRT1 and SIRT3 in tumor suppression is controversial." (PMID 35629426, 2022). "The most important tumor suppression role of SIRT3 is that it hinders cancer metabolism changes via the inhibition of hypoxia-inducible factor-1a (HIF1α)." (PMID 35927590, 2022). "In a word, the impact of SIRT3 on chemotherapy drug resistance varies with tumor type, which needs further study." (PMID 35832551, 2022). "Sirt3 knockdown also increases tumorigenesis in xenograft models, while its overexpression decreases tumor formation." (PMID 35938164, 2022). "A previous study showed that SIRT3 exerts tumor suppressive effects by suppressing ROS and regulating HIF-1α." (PMID 36211825, 2022). "It was found that SIRT3 acts as a tumor suppressor in HCC by inducing apoptosis through the glycogen synthase kinase-3β (GSK-3β)/Bax signaling pathway." (PMID 35159089, 2022). "The function of SIRT3 is different in different tumor tissues and normal tissues, which is related to the specificity of tumor cell type and the cellular context." (PMID 35832551, 2022). "For instance, transplantation of sh-SIRT3 cells in nude mice resulted in rapid tumor growth and larger tumors." (PMID 36581622, 2022). "Other studies also showed an increase in Ki-67 in knockout Sirt3 female mice ER+ tumors, a marker for human luminal B breast malignancies." (PMID 35453320, 2022). "Only for advance NSCLC, high vs. low tumour folate was significantly associated with the overexpression of MCT1, MCT4, LDHA, SLC7A5, SIRT3, and GLUD1." (PMID 36615660, 2022). "SIRT3-mediated effects on mitochondrial metabolism reprogramming by regulating ROS levels are crucial for the chemoresistance of tumor cells." (PMID 35832551, 2022). "SIRT3 has also been found to be involved in the regulation of cancer occurrence and development, However, its function can vary depending on the tumor type, being an oncogene or tumor suppressor gene, for example." (PMID 34747319, 2022). "Down-regulation of SIRT3 promotes tumor metastasis ability, in which it plays a tumor suppressor role." (PMID 35832551, 2022). "GC patients had reduced SIRT3 expression and it had reverse correlation with changes observed clinically, including tumor differentiation, stage and infiltration." (PMID 36499440, 2022). "In this regard, SIRT3 is considered a key scavenger of ROS in cells by playing a tumor-suppressing effect." (PMID 35832551, 2022). "Sirtuin 3 (SIRT3) is a mitochondria deacetylase which has been proposed to be an oncogene or tumor suppressor, with the predominance of these contrasting roles varying among different types of malignancies." (PMID 34831420, 2021). "Based on a number of studies, SIRT3 has been shown to act either as a tumor suppressor or promoter depending on the cell milieus." (PMID 33937086, 2021). "Glucose, hexokinase, PKM2, lactate, PDH, PDK1, SIRT1, and SIRT3, are essential glycolytic and mitochondrial metabolism enzymes controlling tumor progression or regression." (PMID 34771733, 2021). "The analysis of tumour-infiltrating CD8+ T cells showed that the frequency of Sirt3 K223R donor CD8+ T cells (H-2Kb+) was higher than that of Sirt3 WT donor CD8+ T cells." (PMID 34272364, 2021).
tumor (continued). "SIRT3 functions as a mitochondrial TS where, when Sirt3 has been genetically deleted, a tumor-permissive phenotype has been observed using both in vitro assays that measure transformation and tumorigenesis using in vivo murine models." (PMID 33867840, 2021). "In HE staining, we found the same trend, indicated that Sirt3 knockdown tumor cell was more severely damaged by irradiation at the same dose." (PMID 34405009, 2021). "At the same time, the proliferation ability of tumor cells in Sirt3 knockdown group was significantly weaker than that in Control group and Sirt3 OE group, indicated that the inhibit ability of radiation in this group was much stronger." (PMID 34405009, 2021). "The knockdown of SIRT3 expression in tumor growth increases ROS production and focal adhesion kinase (FAK) activation." (PMID 34717757, 2021). "We testified that miR-224 targeted the 3’-UTR of SIRT3, suggesting that miR-224 functioned its oncogenic effects by negatively regulating SIRT3, a tumor-suppressive gene in NSCLC." (PMID 33819917, 2021). "Loss of SIRT3, or reduced SIRT3 activity due to lower NAD+/NADH levels, accelerates tumor formation, accompanied by heightened ROS." (PMID 33605027, 2021). "Genetic deletion of Sirt3 leads to a tumor-permissive phenotype, as shown using both in vivo models and in vitro assays that measure transformation and/or tumorigenesis, suggesting that SIRT3 functions as a mitochondrial TS." (PMID 33867840, 2021). "As expected, sh‐SIRT3 + oe‐NC treatment strikingly promoted tumor volume and weight relative to sh‐NC + oe‐NC, which was reversed by CDT1 overexpression." (PMID 33655712, 2021). "With regard to SIRT3, it can be stated that in some types of cancer, SIRT3 appears to function as a tumor promoter." (PMID 33669567, 2021). "On the basis of understanding the molecular mechanism of UPRmt, targeted downregulation of UPRmt signal molecules, including CHOP, ATF-5, and SIRT3, would retard tumor growth and induce the cell apoptosis." (PMID 34717757, 2021). "The results indicated that GBM tissues had increased levels of GLDC, SIRT3, and pS6K (a hallmark of mTORC1 activity) and decreased levels of ACAT1, NF-X1, and GLDC K514 acetylation in comparison to non-tumor tissues." (PMID 34244482, 2021). "The tumor suppressive role of SIRT3 is mainly mediated by reversing the Warburg-like metabolic reprogramming." (PMID 34829708, 2021). "Next, we found that in the Sirt3 knockdown group, radiation-induced apoptosis of tumor cells was more extensive and severe, reflected its better radiation sensitivity." (PMID 34405009, 2021). "Our analysis found marked increase in PCNA, Survivin and VEGF transcripts in SIRT3 overexpressing tumor tissues." (PMID 33937086, 2021). "SIRT3 orchestrates multiple pathways and acts differently in various types of cancer cells, as tumor suppressor but also as tumor promoter." (PMID 34680344, 2021). "Even though Sirt3 shows a tumor-suppressive role during growth, it has a critical role during matrix detachment and colonization." (PMID 34829708, 2021). "A large number of studies have confirmed that the stability regulation of SIRT3 plays an important role in the regulation of oxidative stress in tumour." (PMID 34841698, 2021). "Significant decreases in PCNA, Survivin and VEGF transcripts were observed in SIRT3 knockdown tumor tissues." (PMID 33937086, 2021). "SIRT3 expression was assessed in isolated tumor tissues and found a marked increase in SIRT3-Flag xenografts." (PMID 33937086, 2021). "Similar results were noticed at the protein level for PCNA, Survivin and VEGF in SIRT3 knockdown tumor tissues." (PMID 33937086, 2021). "Our data demonstrated that SIRT3 knockdown abrogated tumor growth and/or tumor establishment abilities in BRAF-mutant G361-xenografted mouse model." (PMID 33937086, 2021).
tumor (continued). "At day 7 post-transplantation, we inoculated MC38-OVA tumour cells into the recipient mice subcutaneously and observed drastically delayed tumour growth in the Sirt3 K223R TM cell-transplanted mice compared with that in the Sirt3 WT TM cell-transplanted mice." (PMID 34272364, 2021). "We also analyzed the levels of PCNA, Survivin and VEGF transcripts and protein in SIRT3 overexpressing (Hs294T-SIRT3-Flag) tumor tissues." (PMID 33937086, 2021). "As known, SIRT3 is an important cell oxidative stress regulator; especially it participates in the regulation of ROS in many tumour fields." (PMID 34841698, 2021). "In this way, SIRT3 maintains the mitochondrial homeostasis and increases survival and adaptive RR in tumor cells." (PMID 34900673, 2021). "We have also revealed in the past that SIRT3-mediated mitophagy reduces the apoptosis of tumor cells in hypoxia environments, which provides new ideas for tumor prevention and treatment." (PMID 34912814, 2021). "Our analysis predicted the inhibition of cell viability, cell proliferation, tumor growth, and increased apoptosis in response to SIRT3 knockdown, which is in agreement with our in vivo findings." (PMID 33937086, 2021). "And also, drugs that target the CHOP/SIRT3/NRF1/2 signal pathway should achieve maximum tumor death or eradication efficacy." (PMID 34717757, 2021). "Mitochondrial function, including metabolism, ATP generation and the oxidative stress response, is critically regulated by SIRT3, the major deacetylase within the mitochondrial matrix acting as a tumor suppressor by inhibiting the Warburg effect." (PMID 34680344, 2021). "Consistently, Sirt3 K223R T cells (H-2Kb+) were markedly more abundant in MC38-OVA tumour tissue than Sirt3 WT T cells." (PMID 34272364, 2021). "Further, the Kaplan-Meier analysis showed that SIRT3 overexpression resulted in a significant survival detriment, in terms of reaching the tumor cutoff size 20 mm in one dimension." (PMID 33937086, 2021). "SIRT3 can act like a tumor suppressor as well as an oncogene, and thus modulate cell death by affecting the main regulatory factors and their signaling pathways in cancer." (PMID 32002124, 2020). "Since it is unclear if this effect is mediated through the estrogen receptor alpha (ERα) signaling pathway, in this study, we aimed to determine if the tumor-suppressive function of Sirt3 in MCF-7 cells interferes with their response to E2." (PMID 32244715, 2020). "In patients with low FDG uptake, low membranous GLUT1 expression, low Ki67 expression, and high SIRT3 expression were observed in the tumor region." (PMID 32306906, 2020). "SIRT3 in mitochondria will provide an advantage to ATM deficient cancer cells by stimulating glutamate and glutamine utilization thereby promoting tumor proliferation." (PMID 33273545, 2020). "Conversely, the induction of SIRT3 was able to efficiently reduce tumor proliferation via an anti-Warburg effect mediated by the HIF1α/PDK1/PDHA1 pathway." (PMID 32138158, 2020). "In tumor cells, SIRT3, as the major mitochondrial deacetylase in the Sirtuin family, promotes mitochondrial respiration and inhibits HIF-regulated glycolysis." (PMID 33109235, 2020). "As members of the sirtuin family, SIRT1 AND SIRT3 have been shown to possess a tumor suppressor function (45, –, 50)." (PMID 31932479, 2020). "It has been shown that Sirt3 has a bifunctional role in cancer, acting as both oncoprotein and tumor suppressor, depending on the tissue and cancer-type specific metabolic programs." (PMID 32244715, 2020). "SIRT1 effects are cell-dependent, allowing SIRT1 and SIRT3 to have differential effects in the cells of the tumour microenvironment." (PMID 33375613, 2020). "Consistent with previous results with other tumor types, we found high SIRT3 and low Ki67 expression in the low glycolytic group of patients with HCC." (PMID 32306906, 2020).